KRAS (KRas proto-oncogene, GTPase)
Diseases named in the same sentence as KRAS in open-access papers (continued):
Sharing a sentence is not in itself a finding about the gene and the disease.
tumor (continued). "The prevalence of KRAS WT–amplified tumors across 34 tumor types was assessed across TCGA dataset." (PMID 39711431, 2025). "However, exosomes can also facilitate tumor progression by promoting metastasis through integrin-mediated pathways and carrying oncogenic drivers such as KRAS, VEGF, and PD-L1." (PMID 40149276, 2025). "Consequently, more KRAS inhibitors are being discovered and intensively studied across multiple tumour types based on targeting various pathways." (PMID 41463025, 2025). "Oncogenic KRAS results in gene expression changes in fibroblasts in the tumor microenvironment." (PMID 39782689, 2025). "Notably, “Interferon Alpha Response,” “Angiogenesis,” “Hedgehog,” “Apical Junction,” and “KRAS Signaling” were upregulated in tumor samples and downregulated in the UPCI-SCC-090 cell line following JQ1 treatment." (PMID 41323280, 2025). "We further show that the inhibitor of USP25 could destabilize KRAS in cancer cells and was efficacious in blocking tumor xenograft growth in mice." (PMID 40473213, 2025). "Here, we discuss how KRAS allelic imbalances can arise during tumor evolution." (PMID 40227826, 2025). "Furthermore, samples with 5–10% tumor content, including those from EGFR_12, EGFR_2, KRAS_18, and KRAS_26, clustered together with other samples harboring the same mutation." (PMID 40621945, 2025). "It remains unclear whether oncogenic KRAS plays a role in CAF-mediated tumor progression and chemoresistance in PDAC." (PMID 39810420, 2025). "Exploratory studies of treatments targeting KRAS and tumour stroma, including TGFβ, may in addition provide avenues for the subgroup of non-responders to ICB." (PMID 41115454, 2025). "Therefore, fine-tuned KRAS-MAPK activation is required for tumor cells to survive and concurrently evade the detrimental effects of their metabolic adaptations." (PMID 41028058, 2025). "GSEA identified enrichment of genes involved in KRAS signaling in tumours with high SP7 expression." (PMID 40192943, 2025). "This difference may be tissue-specific, indicating that the role of KRAS activation varies across different tumor types." (PMID 40523964, 2025). "A statistically significant difference was observed in lymph node enlargement between KRAS wild‐type and mutant groups in the training set (p = 0.009), and in the test set, a significant difference was found in maximum tumor diameter between the two groups (p = 0.039)." (PMID 40653800, 2025). "Thus, as it has been previously explained, more comprehensive analyses of KRAS copy number changes are needed in pure tumor cell populations and single-cell studies." (PMID 40227826, 2025). "Such precision-driven approaches may exploit signals that tip the macrophage balance toward an M1-like state, thereby bolstering tumor-directed cytotoxicity, or disrupt KRAS-dependent immunosuppression in synergy with established immunotherapies." (PMID 40607411, 2025). "Enriching and balancing radiomic datasets based on clinical information such as tumor stage, KRAS submutations, or multi-scanner data may yield more promising results in the future." (PMID 39860023, 2025). "Linsitinib-mediated IGF-1R inhibition was confirmed by immunoblot analysis of IGF-1R, AKT, and cleaved PARP in residual cancer cells, while apoptosis was quantified by flow cytometry of GFP-labeled cells; delayed tumor recurrence upon KRAS reactivation validated dormancy eradication in vivo." (PMID 41404065, 2025).
tumor (continued). "The discrepancy between these studies could be due to the different tumor samples and/or the differences in the sensitivity of the technologies used to detect the KRAS peptides." (PMID 39846249, 2025). "With regard to the somatic KRAS G12V mutation found in the tumor, it has to be stated there is currently no specific inhibitor for this variant in clinical use." (PMID 40519304, 2025). "Recent research has also shown elevated levels of AIFM2 in KRAS mutant tumors versus non-tumorous tissue, with elevated levels linked to tumor initiation and ferroptosis resistance." (PMID 39617061, 2025). "This and other trials indicate that Exportin 1inhibitor may find applicability in KRAS mutant tumor patient population." (PMID 41394580, 2025). "In addition, the biological interplay of PSGs and KRAS signaling pathway as well as their involvement in the tumor immune modulation should be further examined through wet-lab experiments." (PMID 40257008, 2025). "With a stable genetic background, SMMC‐7721 and SMMC‐7721‐knockdown KRAS cells were respectively injected s.c. into the flanks of 5‐6‐week‐old Balb/c nude mice treated with vehicle chow or NSC48160 through daily intraperitoneal injection after tumor genesis." (PMID 40390765, 2025). "Furthermore, following treatment with KRAS inhibitors, the tumor immune microenvironment transiently shifts to a less immunosuppressive state, exhibiting heightened sensitivity to therapies that promote antitumor immune responses." (PMID 41584578, 2025). "In contrast, KRAS mutant tumours had lower immune cell infiltration compared to KRAS wild type." (PMID 40362630, 2025). "However, due to differences in PD-L1 testing across centres, the authors were not able to determine if this was due to the higher PD-L1 expression previously reported in KRAS mutant tumours." (PMID 40362630, 2025). "Additionally, in KRAS mutant LUAD, the tumor suppressors LKB1/STK11 and KEAP1 are frequently mutated, both of which have been shown to drive immune evasion." (PMID 40849659, 2025). "Dysregulation of PTTG genes may inhibit cell cycle progression and counteract the proliferative effects of EGFR/KRAS signaling, leading to reduced tumor growth." (PMID 40877987, 2025). "In addition to NY-ESO-1, other tumor neoantigens, such as mutant KRAS G12D and KRAS G12V, are being explored as targets for engineered TCR/adoptive T-cell therapy in solid tumors." (PMID 39576208, 2025). "Among oncogenic KRAS mutations, many G12 and G13 mutations only significantly impair GAP-mediated hydrolysis and only Q61 mutations reliably impair intrinsic GTP hydrolysis, leading to the sustained activation of effector pathways and driving tumor growth." (PMID 40970755, 2025). "KRAS, NRAS, and BRAF hot-spot mutations statistical analysis at both nucleotide and protein changes offers a more nuanced perspective and granular picture underlying mutational processes driving tumor formation in different colon regions." (PMID 39857025, 2025). "However, resistance to targeted KRAS inhibitors almost inevitably occurs; resistance can be driven by tumor cell–intrinsic changes or by changes in the microenvironment." (PMID 39782689, 2025). "Increasing the dose may enhance anti-KRAS G12C activity, potentially overcoming resistance driven by the amplified target protein and restoring anti-tumor efficacy." (PMID 40110764, 2025). "Heinemann and colleagues investigated the comparative effectiveness of cetuximab and the anti-vascular epidermal growth factor-A (VEGF-A) antibody bevacizumab in combination with the chemotherapy regimen (FOLFIRI) in the FIRE-3 study, which included 592 patients with KRAS exon 2 wild-type tumours." (PMID 40940907, 2025).
tumor (continued). "IDO-1 positivity in tumor cells was found to be significantly associated with OS in the univariate setting and in the multivariable model where variables including age, sex, histology, stage, EGFR, KRAS and PD-L1 status were included." (PMID 40475772, 2025). "Interestingly, KEAP1/STK11 co-mutations occurred more frequently than KRAS/KEAP1 or KRAS/STK11 co-mutations, suggesting a functional synergy between NRF2- and LKB1-regulated pathways in tumor progression." (PMID 40427178, 2025). "In a multivariable analysis including sex, ancestry, smoking, EGFR mutations, KRAS mutations, and mutational signature ID2 in relation to tumor latency, ID2 had the strongest effect size, followed by EGFR mutations and sex, suggesting an independent impact of these factors on LUAD evolution." (PMID 40161734, 2025). "Although our preclinical data suggest a threshold for the KRAS WT CN of 7 that predicts sensitivity to BI-2493, retrospective analysis of tumor samples derived from patients treated with a pan-KRAS inhibitor will be required to further validate this threshold in the clinical setting." (PMID 39711431, 2025). "Given that KRAS mutations are common in LUAD and associated with aggressive tumor behavior, this link suggests that PSGs may contribute to tumor progression through modulation of KRAS-related pathways." (PMID 40806565, 2025). "Notably, BI-3406 is the first orally available SOS1–KRAS interaction inhibitor and has restricted the proliferation of most tumor cells by reducing KRAS-GTP levels in KRAS mutant cancers." (PMID 40731832, 2025). "KRAS mutations also drive the secretion of cytokines such as IL-6 and GM-CSF, activating pro-inflammatory pathways (e.g., JAK/STAT3) and recruiting MDSCs, further dampening anti-tumor immunity." (PMID 40805153, 2025). "These cells exhibit elevated KRAS and CNV mutation burden, conferring tumor-initiating potential." (PMID 41255572, 2025). "For example, Lin showed that knockout of autophagy gene ATG5 impairs KRAS G12V-driven tumor growth." (PMID 39806421, 2025). "The effectiveness of cetuximab is confined to patients with wild-type KRAS tumours." (PMID 40940907, 2025). "Improvements in understanding RAS signaling, RNA, and nucleic acid chemistry, as well as the role of the tumor microenvironment, have sparked a paradigm shift in the approach to KRAS inhibition and suggested the potential for several novel combination therapies." (PMID 41309533, 2025). "To investigate whether REGγ promotes the progression and malignancy of KRAS-mutant cancers by cooperating with oncogenic KRAS, we conducted cell viability assays to examine the effects of REGγ knockdown on tumor cell growth in KRAS isogenic cell lines." (PMID 40091835, 2025). "To understand the phenotypic patterns and clinical outcomes observed, we integrated transcriptomic data to assess whether variations in the cells of origin and tissue microenvironment influenced KRAS-mediated tumor behavior." (PMID 41375035, 2025). "EMT promoted tumor invasion and metastasis; E2F/G2M pathway activation accelerated cell proliferation, and KRAS suppression may contribute to treatment resistance." (PMID 41296429, 2025). "Oncogenic KRAS results in gene expression changes in epithelial cells in the tumor." (PMID 39782689, 2025). "Unlike KRAS mutations that reflect tumor-intrinsic signaling or CA19–9 as a nonspecific secretory product, UBASH3B expression directly quantifies NK cell-mediated immunosuppression while predicting differential chemotherapy responses." (PMID 40486509, 2025).
tumor (continued). "Conversely, KRAS mutations alone did not lead to tumor formation regardless of DSS administration, suggesting that KRAS mutations alone are insufficient for tumorigenesis." (PMID 41285904, 2025). "GEMMs have been key in establishing that mutant KRAS is also necessary for tumor maintenance." (PMID 40829181, 2025). "Two clonal LUAD tumor pairs were misclassified as non-clonal by all panels due to discordance in KRAS mutation status." (PMID 40373350, 2025). "Although the index detection of DCTN1–ALK was tissue-based, subsequent resistance profiling relied on cfDNA; therefore, we cannot determine whether the KRAS-amplified sub-clone originated from the primary tumor, bone metastases, or both." (PMID 41246301, 2025). "The results showed that KRAS was also highly expressed in HCC tumor tissues." (PMID 41184244, 2025). "Notably, clinical studies revealed that the KRAS G12C inhibitor treatment can robustly induce the production of IFNs in the tumor 7,27." (PMID 40585984, 2025). "Furthermore, integration of Fluor-HPLC with syngeneic mouse models provided insights into KRAS activation dynamics in tumor tissues and evaluated the effectiveness of targeted therapeutics." (PMID 40286847, 2025). "Clinical trials with BI-2865 are currently not yet ongoing, but in preclinical stage, BI-2493, which is a structural analog of BI-2865 that was optimized for in vivo administration, attenuated tumor growth in mice bearing KRAS G12C, G12D, G12V, and A146V mutant models." (PMID 40970755, 2025). "Although additional KRAS-mutant cancer cell lines could be examined, the mechanistic conclusions of this study are strengthened by the inclusion of tumor biopsies from three mtKRAS-positive patients." (PMID 41459907, 2025). "Moreover, in cetuximab-resistant PDX models and mouse models harboring KRAS or BRAF mutations, HTI-1511 significantly inhibited and even reversed tumor growth." (PMID 40469310, 2025). "Therefore, inhibiting canonical KRAS signaling, or using combinations based on these inhibitors, sensitizes tumor cells to immune checkpoint inhibitors, presenting an opportunity to explore such concepts in clinical settings." (PMID 39253995, 2025). "Knocking out Dhx15 in mice with KRAS p.G12D mutant CRC reduces tumor progression." (PMID 40231893, 2025). "This improved response might be linked to the elevated levels of tumor-infiltrating lymphocytes (TILs), TMB, and immunogenicity observed in KRAS-mutant NSCLCs." (PMID 40524071, 2025). "Additionally, therapeutic vaccines that target mutant KRAS proteins, such as Moderna’s mRNA-5671, are being investigated to elicit an immune response capable of recognizing and eliminating KRAS-mutant tumor cells." (PMID 40002297, 2025). "This delivery method has effectively inhibited KRAS mutation without affecting the wild-type KRAS and reduced tumour cell growth and migration in both in vitro and In vivo models of NSCLC." (PMID 39820726, 2025). "Even if the ctDNA mutation VAF has been previously associated with tumor load and metastatic burden, pretreatment levels of detectable KRAS G12C–mutant ctDNA were associated with neither tumor response nor survival outcomes under sotorasib therapy." (PMID 40445863, 2025). "Meanwhile, the accumulation and exploitation of metabolic pathways offer the “microenvironmental support” for immune suppression and the maintenance of inflammation, which ultimately work synergically to drive the tumor immune microenvironment into a suppressive state in KRAS-mutant tumors." (PMID 41184283, 2025). "Similarly, sirpiglenastat (DRP-104), a pro-drug version of DON, reduces tumor growth in KRAS driven-PDAC." (PMID 39806421, 2025).
tumor (continued). "Furthermore, mutant KRAS contributes to tumor progression by secreting inflammatory cytokines such as GM-CSF and IL-6, which recruit immune and stromal cells." (PMID 41514544, 2025). "In the context of PDAC, one of the most significant pathways through which KRAS drives tumour progression is via the activation of the class 1 phosphoinositide 3-kinase (PI3K) enzymes and their synthesis of the lipid signal PIP3, which is removed by the tumour suppressor PTEN." (PMID 40723241, 2025). "The TME, composed of stromal and immune cell populations, plays a critical role in modulating tumour aggressiveness and treatment response to therapeutic agents such as KRAS inhibitors and immunotherapies, thereby limiting the clinical translatability of TME‐exclusive predictive models." (PMID 41025426, 2025). "Harnessing the immune system as an anti-KRAS therapy has the potential for long-lasting benefits; however, it has so far been largely unsuccessful in the clinic and requires better understanding of the immunosuppressive tumor microenvironment of PDAC." (PMID 40829181, 2025). "In the KPC cell–derived orthotopic mouse PDAC model, MRTX1133 treatment significantly decreased glucose utilization of the tumors shown by 18F-FDG PET/CT and also inhibited tumor growth, but interestingly, the inhibition of KRAS dramatically sensitized the KPC tumors to anti–PD-1-based ICB." (PMID 39883522, 2025). "Our previous studies have demonstrated that HLA-A2/KRAS G12V-CD3 BiTE delayed tumor growth." (PMID 41472736, 2025). "We describe an approach to robustly inflame the TME of KRAS-dependent cancers by combining an ASO against the mutated KRAS (KRAS ASO) and immRNA to simultaneously suppress the KRAS mutant and activate the RIG-I pathway in tumor cells, respectively." (PMID 40585984, 2025). "KRAS affects tumor cell development via various lipid metabolism pathways." (PMID 41184283, 2025). "Tumors with mutated KRAS are likely to respond better due to upregulated PD-L1 expression and immune cell infiltration, as opposed to EGFR and ALK-driven tumors, which typically have “cold” tumor microenvironments with fewer immune cells." (PMID 40149342, 2025). "They implied that patients with KRASm might have better response to ICI due to a larger proportion of smokers and a tumor environment with a predominance of immunological cells because of activation of KRAS signaling pathways as well as higher TMB." (PMID 40558308, 2025). "KRAS and BRAF hot-spot mutations were significantly different according to tumor sidedness." (PMID 39857025, 2025). "For instance, many clinical laboratories routinely use tumor gene panels, primarily for solid tumors, which almost invariably include the KRAS gene, enabling the incorporation of detection of individual gene alterations also from the ETV6::RUNX1 ALL samples to diagnostic workflow." (PMID 40634509, 2025). "Additionally, maximum tumor diameter differed significantly between KRAS wild‐type and mutant groups in the test set (P = 0.039)." (PMID 40653800, 2025). "Studies have identified specific mRNAs that function as tumor suppressors by targeting KRAS." (PMID 40805153, 2025).